METTL3 (methyltransferase 3, N6-adenosine-methyltransferase complex catalytic subunit)
Diseases named in the same sentence as METTL3 in open-access papers (continued):
Sharing a sentence is not in itself a finding about the gene and the disease.
gastric cancer (continued). "In gastric cancer cells, METTL3 introduces m6A to the 3′‐UTR region of the PARP1 mRNA where the reader YTHDF1 is recruited; this increases its stability and expression." (PMID 39661414, 2024). "As an example of metabolic reprograming regulation by m6A modifications, Wang and co-workers have shown that METTL3 promotes glycolysis and angiogenesis in gastric cancer." (PMID 38075202, 2024). "The results of this study suggest that METTL3 acts as an oncogene to promote angiogenesis by targeting gastric cancer-related enzymes." (PMID 39678510, 2024). "Intriguingly, miRNA-4429 inhibits METTL3 to suppress m6A-caused stabilization of SEC62 and impairs gastric cancer progression through this way." (PMID 38075202, 2024). "M6A methyltransferase METTL3 has been reported to contribute to oxaliplatin resistance by stabilizing PARP1 mRNA in CD133 + gastric cancer stem cells." (PMID 39731162, 2024). "On the other hand, not only can METTL3 promote the proliferation as an oncogene, but also contribute to the migration and invasion of gastric cancer." (PMID 39009956, 2024). "As previously discussed, HDGF expression is fostered via the METTL3/IGF2BP3-HDGF mRNA axis in an m6A-dependent manner in gastric cancer." (PMID 37280679, 2023). "These two studies suggest that the mutual regulation of ncRNAs and METTL3 has an important impact on the prognosis of gastric cancer patients." (PMID 37781524, 2023). "Meanwhile, METTL3 upregulation was found to exert an analogous effect on participating in gastric cancer progression." (PMID 36875073, 2023). "For example, METTL3 is a key promoter of gastric cancer metastasis in vivo and malignant progression in vitro, activating downstream regulatory networks through regulation of m6A-dependent ZMYM1." (PMID 37344779, 2023). "In gastric cancer, METTL3 has been reported to promote cell proliferation and metastasis through different downstream genes." (PMID 38007439, 2023). "It is interesting to note that recent findings in gastric cancer also suggest a methyltransferase-independent role of METTL3 in malignant cells." (PMID 37192910, 2023). "Analysis of gastric cancer patients (TCGA-STAD) in the TCGA database revealed higher expression levels of METTL3 in tumor samples." (PMID 37822880, 2023). "In gastric cancer cells, METTL3 increases Snail and Slug expression to repress E-cadherin transcription, promoting the occurrence of EMT and tumor metastasis." (PMID 37996892, 2023). "In gastric cancer, METTL3 was found to catalyze m6A in an m6A/DGCR8-dependent manner to process pri-miR-1792 into a mature form." (PMID 37781524, 2023). "In bladder cancer, NSUN2 methylates and stabilizes HDGF mRNA 3′UTR (also stabilized by METTL3 in gastric cancer) promoting cancer metastasis." (PMID 37369946, 2023). "In detail, METTL3 was identified as the direct target of miR-1269b and miR-338-5p, thus inhibiting gastric cancer development." (PMID 36614216, 2023). "Aberrant m6A methylation levels were observed in gastric cancer cells, and upon knocking down METTL3, the m6A methylation levels in gastric cancer cells were significantly reduced." (PMID 37822880, 2023). "Methylated RNA immunoprecipitation-qPCR (MeRIP-qPCR) and RNA stability analysis were employed to explore the mechanism of METTL3 in gastric cancer progression." (PMID 37344779, 2023). "Collectively, our findings suggest that METTL3 knockdown can augment the sensitivity of Gastric cancer cells to Oxaliplatin by impeding DNA repair processes." (PMID 37822880, 2023). "In gastric cancer cells, METTL3 stimulates the m6A modification of heparin binding growth factor (HDGF) mRNA, and IGF2BP3 then directly binds to the m6A-modified mRNA and enhanced RNA stability." (PMID 37192910, 2023). "In gastric cancer, METTL3 cooperates with HuR to enhance the RNA and protein stability of ZMYM1 in an m6A-dependent manner." (PMID 37996892, 2023).
gastric cancer (continued). "In addtion, the functional role of LINC00240/miR-338-5p/METTL3 axis was investigated in regulating the aggressiveness of gastric cancer cells." (PMID 37365581, 2023). "METTL3 is a key catalyst for m6A modification, which display carcinogenic effects in breast cancer, endometrial cancer, and gastric cancer." (PMID 36710350, 2023). "It has been demonstrated that P300 regulates histone H3 acetylation at lysine 27 (H3K27ac) and promotes METTL3 transcription in gastric cancer." (PMID 36550779, 2023). "Dysregulation of m6A regulatory proteins has been noted in stomach cancer, exemplified by the upregulation of Methyltransferase-like 3 (METTL3), a critical m6A “writer,” in gastric cancer tissues, which has been associated with an unfavorable prognosis." (PMID 37822880, 2023). "The potential of using METTL3/14 as a direct target for anti-tumor immunotherapy in gastric cancer patients to promote treatment efficacy warrants further exploration." (PMID 38187373, 2023). "In gastric cancer, METTL3-mediated SPHK2 m6A modification followed by YTHDF1 facilitates translation initiation through interacting with eIF3a, which in turn upregulates the translation efficiency and promotes tumor progression." (PMID 36830614, 2023). "In gastric cancer, METTL3 stabilizes hepatoma-derived growth factor (HDGF) that activates GLUT4 and ENO2 expression and subsequent angiogenesis and glycolysis that promote liver metastasis." (PMID 37369946, 2023). "In gastric cancer, aberrant METTL3 has long been recognized as a marker of poor patient prognosis, and enhanced METTL3 up-modulated m6A modification of ZMYM1 mRNA, DEK mRNA or HDGF mRNA to induce tumor growth and distant metastasis." (PMID 37344779, 2023). "In gastric cancer, METTL3 enhances the expression of THAP7-AS1 by m6A modification to improve the migration and invasion capacity of tumor cells." (PMID 37996892, 2023). "In gastric cancer, high METTL3 expression significantly elevates glucose uptake and lactate production." (PMID 37996892, 2023). "For example, by stabilizing the transcripts of ARHGAP5 and promoting ARHGAP5 expression by recruiting METTL3, the chemoresistance of gastric cancer cells can be enhanced by lncRNA ARHGAP5-AS1." (PMID 38102645, 2023). "For example, METTL3 promotes gastric cancer glycolysis and progression by regulating the m6A modification of hepatoma-derived growth factor (HDGF) mRNA." (PMID 37340443, 2023). "In gastric cancer, the upregulation or knockdown of METTL3 is followed by an increase or decrease respectively in m6A levels." (PMID 38053093, 2023). "METTL3 knockdown induced apoptosis in OXA-resistant Gastric cancer cells and enhanced their sensitivity to Oxaliplatin." (PMID 37822880, 2023). "Quantitative real-time PCR (qRT-PCR) was constructed to detect the expression of METTL3 in gastric cancer cell lines and patient tissues." (PMID 37344779, 2023). "In gastric cancer, phosphorylated Smad2/3 is increased in the nucleus and initiates transcription of METTL3." (PMID 37996892, 2023). "Our findings revealed that the knockdown of METTL3 significantly impeded the proliferation and migration of Gastric cancer cells." (PMID 37822880, 2023). "It was reported that methyltransferase-like 3 (METTL3)-mediated m6A modification of HDGF mRNA promotes gastric cancer (GC) progression and has prognostic significance." (PMID 36866236, 2023). "Another important finding is that METTL3 knockdown and OXA-induced Gastric cancer cell death are additive, and the targeted METTL3 can assist Oxaliplatin treatment." (PMID 37822880, 2023). "For example, in human gastric cancer, up-regulation of METTL3 can promote tumor angiogenesis, glycolysis, and target MYC pathway, thus serving as a potential prognostic biomarker and therapeutic target for this malignancy." (PMID 35794583, 2022). "METTL3 facilitated oxaliplatin resistance via enhancing the stability of PARP1 mRNA in gastric cancer stem cells." (PMID 36003776, 2022).
gastric cancer (continued). "Overexpression of METTL3 promoted the proliferation and migration of gastric cancer cells, while the knockdown of METTL3 had the opposite effect." (PMID 35742899, 2022). "In this study, we found that METTL3 promoted the proliferation and migration of gastric cancer cells, and the knockdown of DEK reversed the effect of METTL3 on the proliferation and migration of gastric cancer cells." (PMID 35742899, 2022). "In gastric cancer, METTL3 promoted the m6A modification of HDGF mRNA, and the m6A reader IGF2BP3 directly recognized and bound to the m6A site on HDGF mRNA and enhanced HDGF mRNA stability." (PMID 35144642, 2022). "Previous studies have shown that METTL3 attributes to the oncogenesis of bladder cancer, acute myeloid leukemia, lung cancer, liver cancer, breast cancer, and gastric cancer." (PMID 35094011, 2022). "m6A methyltransferase METTL3 facilitated oxaliplatin resistance in gastric cancer (GC) stem cells by substantial DNA damage repair." (PMID 36517820, 2022). "Studies have discovered that METTL3 is highly expressed in gastric cancer cells, and that knockdown of METTL3 dramatically reduced cell proliferation, migration, and invasion in human gastric and HCC cancer cells." (PMID 36003776, 2022). "Clinical assays disclosed that overexpression of METTL3 predicted a poor outcome of gastric cancer patients." (PMID 35265129, 2022). "It was reported that high expression of METTL3 was related with a poor prognosis in gastric cancer patients." (PMID 35280730, 2022). "In gastric cancer, METTL3 promoted the mRNA stability of Sec62, which functions as a negative regulator of apoptosis, in an m6A/IGF2BP1 -dependent manner." (PMID 35350378, 2022). "Accumulating evidence suggests that METTL3 exhibits tumorigenic functions in a wide range of malignancies, including breast, colorectal, and gastric cancers." (PMID 35255776, 2022). "Similar studies in gastric cancer cells showed that METTL3 promotes m6A modification of the mRNA of recombinant protein hepatoma-derived growth factor (HDGF), whereas IGF2BP3 directly recognizes and binds to the m6A site on HDGF mRNA, enhancing its stability." (PMID 36064747, 2022). "In gastric cancer, METTL3 was upregulated and the elevated METTL3 level was an important predictor for poor prognosis of the patients." (PMID 36058919, 2022). "Overexpression of miR-1269b can down-regulate METTL3, thereby inhibiting the proliferation, migration, and invasion of gastric cancer cells." (PMID 35252180, 2022). "miR-1269b is low expressed in gastric cancer, while overexpression of miR-1269b can inhibit the proliferation, migration, and invasion of tumors by targeting METTL3." (PMID 35252180, 2022). "For instance, METTL3 promoted neovascularization in stomach cancer, but suppressed expression of angiogenic factors in sorafenib-resistant HCC." (PMID 36291060, 2022). "In Gastric Cancer (GC), overexpression of METTL3 (a writer) promoted metastasis to the liver in vitro and in vivo, and it also stimulated the modification of adenosine to m6A, enhancing mRNA stability." (PMID 35186927, 2022). "In gastric cancer, miR-4429 acts as a tumor suppressor by targeting METTL3 to inhibit m6A methylation-induced stabilization of SEC62 and reduce tumor growth." (PMID 35794625, 2022). "For example, LINC00470 inhibits the PTEN stability by binding to METTL3 and promotes gastric cancer progression." (PMID 36032659, 2022). "Elevated expression of METTL3 in gastric cancer contributes to angiogenesis and liver metastasis by promoting HDGF secretion to support glycolysis." (PMID 35794625, 2022). "In gastric cancer, P300 was found to promote METTL3 transcription by mediating histone H3 acetylation." (PMID 36429032, 2022). "The high expression of methyltransferase-like 3 (METTL3) can promote tumor angiogenesis in gastric cancer tissues." (PMID 35628460, 2022). "For instance, as a main RNA N6-adenosine methyltransferase, METTL3 was highly expressed in gastric cancer." (PMID 35265129, 2022).
gastric cancer (continued). "METTL3 was also taken part in linc00240-induced gastric cancer progression via targeting miR-338-5p." (PMID 36003776, 2022). "And in this study, through immunohistochemistry on gastric cancer tissue samples of 17 patients, it was found that in gastric cancer tissues, the positive rate of PP2Acα was 2/17 (11.8%), and the positive rate of METTL3 was 14/17 (82.4%)." (PMID 34485508, 2021). "The expression of METTL3 mRNA in gastric cancer tissues was significantly different from that in adjacent tissues." (PMID 34394353, 2021). "Another significant research demonstrated that METTL3 promotes gastric cancer progression and has prognostic significance." (PMID 33976730, 2021). "For example, aberrant m6A modifications of BATF2 mRNA by METTL3 repressed its expression in gastric cancer, which contributes to the tumor growth and metastasis." (PMID 33726814, 2021). "Hepatoma-derived growth factor (HDGF) mRNA is a key downstream target of METTL3 in gastric cancer (GC)." (PMID 34858499, 2021). "For instance, miR-548b-3p represses the progression of lung cancer; miR-1269b represses the progression of gastric cancer development via regulating methyltransferase-like 3 (METTL3)." (PMID 34251961, 2021). "In gastric cancer, miR-4429 was observed to target and reduce the mRNA expression of METTL3, inhibiting the stability of SEC62 induced by m6A, thereby inhibiting the proliferation and inducing apoptosis of gastric cancer cells." (PMID 34108450, 2021). "In gastric cancer, METTL3, guided by an antisense lncRNA of ARHGAP5, ARHGAP5-AS1, methylates ARHGAP5 mRNA and promotes its stability to enhance cisplatin resistance." (PMID 34315512, 2021). "Another study has elucidated that miR-4429 prevented the onset of gastric cancer via targeting METTL3." (PMID 33740948, 2021). "To further verify the oncogenic role of METTL3, we inhibited METTL3 in gastric cancer cells SGC7901 to detect its effects on cell cycle and cell proliferation." (PMID 34729106, 2021). "Previous studies show elevated METTL3 expression in gastric cancer tissues and acute myeloid leukemia (AML) cells, which promotes tumor cell proliferation and thereby facilitates cancer progression." (PMID 34535671, 2021). "In the following, taking gastric cancer as an example, METTL3 can promote the development and progression of gastric cancer by mediating m6A RNA modification of HDGF mRNA." (PMID 34660577, 2021). "Analogously, the lncRNA ARHGAP5-AS1 can recruit METTL3 to methylate ARHGAP5 mRNA in gastric cancer cells, thus, increased levels of m6A-ARHGAP5 were predictive of enhanced chemoresistance and poor prognosis." (PMID 34722298, 2021). "The level of METTL3 protein in the gastric cancer cell line was also significantly different from that in the normal cell line." (PMID 34394353, 2021). "It functions as an oncogene in gastric cancer through sponging miR-193b-5p, which exerts its effects by regulating the expression of the downstream target gene METTL3." (PMID 33976730, 2021). "In turn, the overexpression of YAP1 eliminates the inhibitory effect of METTL3 silencing on the proliferation, migration, and invasion of gastric cancer cells." (PMID 34394353, 2021). "For example, lncRNAs ARHGAP5-AS1 and LINC00470 have been revealed to guide METTL3 to specific targets to promote tumorigenesis in gastric cancer." (PMID 34315512, 2021). "In gastric cancer, miR-4429 acts as a tumor suppressor by targeting METTL3 to inhibit m6A-induced stabilization of SEC62 and reduce tumor growth." (PMID 34315512, 2021). "For the first time, this study established that miR-193b-5p directly targets N6-Adenosine-Methyltransferase 70 KDa Subunit (METTL3) in gastric cancer." (PMID 33976730, 2021). "The linear regression analysis showed that the YAP1 level positively correlated with the METTL3 level in human gastric cancer tissues." (PMID 34394353, 2021). "For example, in gastric cancer, METTL3 promotes the pathogenesis by catalyzing the methylation of ZMYM1 or HDGF." (PMID 34489709, 2021).
gastric cancer (continued). "This article proved that m6A methyltransferase METTL3 promoted the proliferation and migration of gastric cancer cells through the m6A modification of YAP1." (PMID 34394353, 2021). "P300-mediated H3K27 acetylation activation present in the promoter region of METTL3 induced the transcription of METTL3, thus promoting tumor angiogenesis and glycolysis in gastric cancer." (PMID 33976730, 2021). "Dysregulation of METTL3 expression has been reported in colorectal cancer, pancreatic cancer and gastric cancer." (PMID 34094960, 2021). "The results revealed that the METTL3 expression level was elevated dramatically in various gastric cancer types compared with normal tissues." (PMID 33976730, 2021). "The present study found that the levels of m6A and METTL3 were significantly higher in gastric cancer tissues and gastric cancer cell lines compared with normal paracancer tissues." (PMID 34394353, 2021). "This study showed that m6A methyltransferase METTL3 promoted the proliferation and metastasis of gastric cancer through the modification of YAP1 mRNA m6A." (PMID 34394353, 2021). "In conclusion, this study showed that m6A methyltransferase METTL3 promoted the proliferation and metastasis of gastric cancer through the m6A modification of the YAP1 pathway." (PMID 34394353, 2021). "Consistent with our findings, a recent study revealed that METTL3 expedites EMT to induce metastasis in gastric cancer." (PMID 33754062, 2021). "For instance, METTL3 can exacerbate EMT in gastric cancer by activation of the zinc finger MYM-type containing 1 signaling, while it can also upregulate the JunB proto-oncogene to mediate the progression of EMT in lung cancer." (PMID 34666602, 2021). "METTL3-mediated m6A plays a pivotal role in the epithelial mesenchymal transition and metastasis of gastric cancer." (PMID 33589575, 2021). "The METTL3-mediated N6-methyladenosine modification is vital for epithelial-mesenchymal transition and metastasis of gastric cancer." (PMID 33976730, 2021). "This research showed that the expression of m6A and METTL3 was upregulated in human gastric cancer tissues and gastric cancer cell lines." (PMID 34394353, 2021). "For example, upregulated METTL3 expression was shown to promote gastric cancer and hepatocellular carcinoma progression by promoting, respectively, epithelial to mesenchymal transition and posttranscriptional silencing of SOCS2." (PMID 34507301, 2021). "Our data show that the m6A level was upregulated in gastric cancers and suppressing m6A by METTL3-knockdown hindered tumor growth and metastasis in vitro and in vivo." (PMID 33037176, 2020). "Recently, several studies reported that METTL3, the core methyltransferase for m6A modification, promotes gastric cancer progression." (PMID 33037176, 2020). "Previous studies have shown that overexpression of METTL3 is closely related to gastric cancer, liver cancer and colorectal cancer 16-18." (PMID 32626532, 2020). "To determine the clinical relevance of METTL3, we tested METTL3 expression in gastric cancer samples of 87 patients who had received radical or palliative gastrectomy." (PMID 33037176, 2020). "In gastric cancer (GC), overexpression of METTL3 can promote the stability of ZMYM1, thereby enhancing epithelial mesenchymal transformation (EMT) process and tumor metastasis." (PMID 33015074, 2020). "METTL3, which expression is correlated with poor prognosis, promotes gastric cancer cell proliferation and liver metastasis by stimulating m6A modification of heparin binding growth factor (HDGF) mRNA." (PMID 33372610, 2020). "METTL3 is significantly increased in gastric cancer tissues compared with control in big crowd data sets and served as a poor prognostic factor for patients with gastric cancer." (PMID 32201509, 2020). "For instance, elevated METTL3 expression promotes gastric cancer progression by mediating m6A modification of HDGF mRNA." (PMID 32419773, 2020).